INS (insulin)
Diseases named in the same sentence as INS in open-access papers (continued):
Sharing a sentence is not in itself a finding about the gene and the disease.
diabetes (continued). "Most reported patients with HNF1B-diabetes (N = 293) and MD (N = 233) are on insulin without treatment studies." (PMID 39025920, 2024). "There is a lack of insulin in type 1 diabetes mellitus, while in type 2 there is insufficient insulin, insulin resistance or both." (PMID 39595804, 2024). "Most participants (525, 62.4%) indicated that they had been diagnosed with diabetes over ten years ago; 827 (98.1%) reported treatment that included either insulin (279, 33.1%), non-insulin agents (184, 21.9%), or a combination (364, 43.2%)." (PMID 38932391, 2024). "Maturity Onset Diabetes of the Young (MODY) is a young-onset, monogenic form of diabetes without needing insulin treatment." (PMID 38719926, 2024). "Since the DCCT study, weight gain and serum lipid levels in patients with diabetes have been related with inadequate eating practices, excess carbohydrates, lack of physical activity and exogenous insulin administration." (PMID 39533433, 2024). "Also, a shared mechanism between PD and type 2 diabetes mellitus (T2DM) is protein aggregation, with α-syn aggregation in PD and amylin aggregation in insulin-producing cells for diabetes." (PMID 39408276, 2024). "At baseline, participants who later developed diabetes had increased glucose and insulin AUCs/iAUCs in response to the MMTT than non-progressors." (PMID 38987291, 2024). "In previous studies, glucose, insulin, and HOMA-IR values increased with an HF diet in male Wistar rats, while they decreased with metformin treatment in male Wistar rats with type 2 diabetes mellitus (T2DM)." (PMID 38884844, 2024). "Type 2 diabetes (T2D) is a form of diabetes mellitus characterized by high blood sugar, insulin resistance, and relative lack of insulin." (PMID 38674024, 2024). "We aimed to compare counterregulatory hormone and symptom responses to hypoglycaemia between people with type 1 diabetes, insulin-treated type 2 diabetes and controls without diabetes, using a standardised hyperinsulinaemic-hypoglycaemic clamp." (PMID 38376580, 2024). "In 2012 (with an update in 2014), an insulin PDA booklet was developed in Malaysia to promote patient centered care through fostering SDM practices and to help patients to make informed decisions about diabetes treatment." (PMID 39546450, 2024). "Diabetes mellitus is a significant global health problem characterized by high blood sugar levels due to either a lack of insulin or insensitivity to it." (PMID 39371721, 2024). "These disruptions are pivotal as they can precipitate abnormal cellular outcomes and contribute to the development of diseases such as Type 2 Diabetes Mellitus (T2DM), emphasizing the critical implications of INS Signaling (INSS) interplays in disease pathology." (PMID 39595105, 2024). "Chart reviews identified noncritically ill patients with pre-existing type 2 diabetes mellitus receiving insulin injections." (PMID 38919469, 2024). "Finally, IGFBP7 knockdown in islets from T2D donors improved insulin secretion, making IGFBP7 a potential drug target in diabetes." (PMID 39280605, 2024). "Diabetes nurse access, but not support staff diabetes course, related to a more than two-fold higher chance of ‘timely’ insulin-initiation both prior to and after adjustments." (PMID 38116986, 2024). "A likely pathogenic KCNJ11 de novo variant (NM_000525.4: c.675C>A, p.Ser225Arg) was identified in a patient who remitted to normal glycemia without any insulin therapy 1 week after diabetes onset." (PMID 38408297, 2024). "A COVID-19 infection can cause hyperglycemia in individuals without diabetes because the virus binds to ACE2 on pancreatic cells, which can impair β-cell function and cause insulin inadequacy." (PMID 39995847, 2024). "The only patient with diabetes requiring insulin who was not admitted to hospital also did not require enteral feeding." (PMID 38392055, 2024).
diabetes (continued). "Diabetes is a chronic condition where the body either does not produce sufficient insulin, produces no insulin at all, or cannot effectively use the insulin it does produce." (PMID 39540008, 2024). "In aggregate, these STZ-diabetic rodent models showed modest metabolic actions on glucose and insulin with L. brevis treatment without reversal of diabetes." (PMID 39619323, 2024). "Type 1 diabetes mellitus (T1D) is a chronic autoimmune disease characterized by the destruction of insulin-producing pancreatic beta cells and an ensuing lack of or low insulin." (PMID 39040994, 2024). "As almond oil displayed anti-diabetes activity in streptozotocin-induced rats, Clostridium_sensu_stricto_1 was positively correlated with FBG, MDA, TNF-α, IL-1β, and Keap1 and was negatively correlated with insulin, body weight, SOD, CAT, Nrf2, and HO-1." (PMID 39403395, 2024). "High levels of apo-CIII are found in individuals with diabetes mellitus compared with individuals without diabetes and are related to reduced insulin sensitivity and apoptosis of pancreatic beta-cells." (PMID 38791405, 2024). "Our study was limited by the dichotomous definition of pre-transplant diabetes (having diabetes requiring treatment with insulin or oral hypoglycemics, but not diet alone)." (PMID 38062242, 2024). "Diabetes mellitus is a chronic disease characterized by hyperglycemia due to either insufficient production of insulin by the pancreas or the body not responding effectively to secreted insulin." (PMID 38255878, 2024). "A meta-analysis of clinical trials revealed that oral supplementation of Mg2+ markedly improves the HOMA-IR index without impacting blood glucose, insulin, or HbA1c levels in patients with diabetes and individuals without diabetes." (PMID 39202546, 2024). "It is has been described, that myostatosis contributes to insulin abnormalities and diabetes, possibly even independent of obesity." (PMID 38777903, 2024). "OAGB had a better success rate for T2DM (95%) in 1 year, even though patients with more serious diabetes underwent OAGB (40% of the patients were on insulin in the OAGB group vs none in the SG group)." (PMID 38833355, 2024). "In the current study, PAD was found to be correlated with diabetes duration, insulin dose, and lipid derangements; interestingly, it was not correlated to HbA1C." (PMID 37831337, 2024). "This is problematic as older studies are unlikely to reflect changes in diabetes treatment, for example the insulin types (human and analogue) or the delivery systems (syringe vs. pen) available." (PMID 38778253, 2024). "This difference could reflect the presence of diabetes status as a component of the HSI algorithm, possibly overestimating the contribution of insulin resistance to MASLD." (PMID 38498227, 2024). "Type 2 diabetes mellitus (T2DM) occurs when the pancreas does not release as much insulin as needed or when cells have decreased sensitivity to insulin." (PMID 38783146, 2024). "Individuals with type 2 diabetes on metformin treatment had higher proglucagon levels, whereas insulin treatment lowered proglucagon to levels below the reference levels of individuals without diabetes." (PMID 38705923, 2024). "A total of 445 million (95% CrI 401–496) adults aged 30 years or older with diabetes were not treated with oral hypoglycaemic drugs nor insulin (59% of those with diabetes), 3·5 times the number in 1990 (129 million, 112–147)." (PMID 39549716, 2024). "In some cases, patients can have insulin levels 300 times above normal but glucose levels that do not exceed the threshold for diabetes." (PMID 39006824, 2024). "Type 1 diabetes mellitus (T1DM) is an endocrine disorder in which pancreatic β cells do not secrete insulin, typically due to autoimmune destruction." (PMID 38579756, 2024). "Currently, the age category and specific kind of diabetes patients for whom the Imperium patch pump, Dibkit insulin pump, and Osmotic WBI are being developed have not been determined." (PMID 39065641, 2024).
diabetes (continued). "The median values of brain insulin signaling measures in participants with diabetes were consistently higher than those in participants without diabetes." (PMID 38029396, 2024). "While insulin has been advocated as the choice of treatment for both HNF1B-diabetes and MD4,127, we found no systematic evidence favoring the use of insulin." (PMID 39025920, 2024). "Bioactive compounds present in drugs marketed for the control of diabetes, such as sitagliptin and alogliptin, act by inhibiting the enzyme DPP-IV or mimicking incretins, which are hormones responsible for stimulating insulin secretion by pancreatic β cells in the presence of glucose." (PMID 39452081, 2024). "The use of noninsulin diabetes medications (all medications under the ATC category A10B) increased during the study period in T2D insulin users." (PMID 38273701, 2024). "Unlike in type 1 diabetes mellitus, where psychiatric issues, particularly depression, often stem from insulin treatment, psychiatric symptoms in WS are more prevalent (30%) and associated with ER stress." (PMID 39064493, 2024). "All patients suffered from the same type of diabetes, which was well controlled without requiring insulin treatment." (PMID 38758998, 2024). "In their study of recent advancements in the development of electrochemical biosensors for the diagnosis of diabetes mellitus, Pavla and Miroslav emphasized new developments in the use of glucose, HbA1c, GHSA, and insulin biomarkers to monitor diabetes more effectively." (PMID 39091901, 2024). "In our study, we did not observe any relationship with the presence of diabetes mellitus, nor with the use of insulin." (PMID 39518373, 2024). "Overexpression of CTRP9 has been shown to decrease insulin and blood glucose levels, indicating that CTRP9 may offer improvements in diabetes." (PMID 39575169, 2024). "Among patients who developed diabetes after age 30 and did not use insulin, the prevalence of DR Was 39%, the cumulative 4-year prevalence was 34%, and the progression to PDR was 3%." (PMID 38645437, 2024). "The only patient with diabetes requiring insulin at baseline who was not admitted for a diabetes-related complication and did not require enteral feeding was able to continue their anti-diabetic regimen throughout CCRT (which included use of an OHG)." (PMID 38392055, 2024). "The risk of BTC seemed to be greater among participants with reduced diabetes durations and those who did not receive treatment with insulin beyond obesity." (PMID 39410050, 2024). "The previous study investigated patients with type 2 diabetes, who were mainly glucose-tolerant with a shorter diabetes duration rather than insulin-dependent." (PMID 38589596, 2024). "The accuracy of CGM device used in our study was previously found not to be affected by BMI, age, type of diabetes, sensor insertion site, insulin administration, or HbA1c level." (PMID 38105282, 2024). "The concept of diabetes mellitus has changed from a monohormornal, insulinocentric (lack of relative insulin quantity and sensitivity), to a bi- or even multihormonal disorder." (PMID 39027470, 2024). "His medical history included type 2 diabetes mellitus managed with insulin, essential hypertension, osteoarthritis, and no previous abdominal operations." (PMID 38737669, 2024). "During diabetes, the absence of insulin or its inability consequences in raised sugar levels in the bloodstream." (PMID 38371502, 2024). "Nineteen attributes are recognised as a standard in all four considered complications, which are age, gender, ethnicity, weight, height, BMI, smoking history, HbA1c, SBP, eGFR, DBP, HDL, LDL, total cholesterol, triglyceride, use of insulin, duration of diabetes, family history of CVD, and diabetes." (PMID 38178670, 2024). "Despite the introduction of new therapies such as the GLP-1 receptor agonists and SGLT2 inhibitors, many people with T2D do not meet the recommended glucose targets and still require insulin to manage their diabetes." (PMID 39390689, 2024).
diabetes (continued). "Fourteen patients had cancer, 11 had type 2 diabetes mellitus (none on insulin, all on oral antidiabetics), eight had atrial fibrillation, and eight had heart failure." (PMID 38951901, 2024). "When present, these symptoms (e.g., feelings of tiredness or weakness) can also signal diabetes device users to validate their glycemic status by checking their CGM, either on their insulin pump or by using a phone application, particularly with uncertain symptoms related to hyperglycemia." (PMID 38846748, 2024). "Although several studies have reported the development of insulin-deficient diabetes mellitus after ICI administration, it is not necessarily a type of insulin-depleted diabetes." (PMID 39722806, 2024). "After endoscopic retrograde cholangiopancreatography (ERCP), the three cases of chronic pancreatitis did not recur, and the child with diabetes mellitus discontinued insulin therapy after 392 days of follow-up." (PMID 39439952, 2024). "The treatment of diabetes with garlic oil in this study improved insulin resistance, possibly through the action of diallyl disulfide (DADS) present in garlic, which promoted increased insulin secretion and improved insulin sensitivity." (PMID 38630691, 2024). "OAGB had a better success rate for T2DM (95%) in 1 year, even though patients with more severe diabetes underwent OAGB (40% of the patients were on insulin in the OAGB group vs none in the SG group)." (PMID 38833355, 2024). "In contrast, type 2 diabetes mellitus (characterized by high blood sugar levels, insulin resistance, and relative deficit of insulin) does not correlate significantly (p = 0.122)." (PMID 38399417, 2024). "During growth hormone therapy, diabetes was diagnosed by OGTT test and insulin therapy was started." (PMID 39766859, 2024). "Diabetes is a chronic disease that occurs when the pancreas does not produce enough insulin or when the body cannot use the insulin it does produce efficiently." (PMID 39124105, 2024). "In the GST, glucose levels temporarily increase and stimulate insulin secretion in subjects without diabetes." (PMID 39459358, 2024). "Individuals with diabetes exhibited higher body mass index (BMI) and fasting insulin levels compared to non-diabetic individuals." (PMID 38351959, 2024). "In a five-day diabetes camp with 60 participants with T1DM, medical nutrition therapy was implemented, among other interventions (lectures and games on insulin therapy and dose adjustments, recognition and management of hypo- and hyperglycemia, and management of diabetes complications)." (PMID 39408305, 2024). "Our study showed that 56.5% of patients used oral medications to control diabetes while 43.5% used insulin and that a high adherence rate to medication (80.4%) did not prevent amputations." (PMID 39781130, 2024). "This resistance to insulin-mediated glucose uptake occurs in >80% of individuals with impaired glucose tolerance (IGT) or type 2 diabetes mellitus and in at least 25% of individuals without obesity and with normal oral glucose tolerance." (PMID 39769002, 2024). "A combination of in-hospital diabetes teams, continuous glucose monitoring (CGM), and operational insulin titration algorithms to act on CGM data might contribute to this need." (PMID 38711112, 2024). "Moreover, 7S,14R-diHDHA augmented the MSC effect on insulin secretion, thus demonstrating that 7S,14R-diHDHA improved MSC amelioration of type 2 diabetic mellitus." (PMID 38533089, 2024). "This analysis, integrating data from a smart insulin pen and CGM, provides insights into the impact of dosing behavior on glycemic outcomes and informs counseling strategies for the diabetes care team, through technologically advanced insulin management for those using MDI therapy." (PMID 37855818, 2024). "The transcriptional activity of hepatic CREB is amplified in diabetes, resulting in high blood sugar and a lack of responsiveness to insulin." (PMID 38674437, 2024).
diabetes (continued). "Type 2 diabetes, which accounts for more than 90% of all diabetes cases, is characterized by a progressive lack of adequate insulin secretion from the β-cells as the result of insulin resistance." (PMID 38535328, 2024). "Type 2 diabetes, resulting from a progressive, non-autoimmune reduction in β-cell insulin secretion, often amid insulin resistance and metabolic syndrome, represents 90-95% of all diabetes cases." (PMID 38469145, 2024). "Additionally, since insulin and IGF-1 are functionally intertwined, the profound consequences of diabetes on insulin function heavily affect IGF-1/IGF-1R activity, and vice versa." (PMID 39638246, 2024). "On the other hand, the activity of catalase in the heart was not affected by diabetes with or without insulin or sarpogrelate treatment." (PMID 39057635, 2024). "Overall, these findings were clearly reassuring for people using or considering the use of insulin but this approach does not seem attractive for the prevention of diabetes." (PMID 39342254, 2024). "This suggests that the one-day outpatient service for diabetes can reduce the postprandial blood glucose of GDM patients and improve insulin resistance by standardizing the patients’ diet and exercise habits, which was consistent with the previous research conclusions." (PMID 39634546, 2024). "Insulin resistance, a condition in which cells do not respond adequately to insulin, plays a crucial role in diabetes and related metabolic disorders." (PMID 38195616, 2024). "While patients’ T1D management skills, such as carbohydrate counting, insulin dose calculations, and insulin-to-carbohydrate ratios, remain crucial components, the introduction of AHCL systems marks a shift towards optimal diabetes control and a significant reduction in patients’ self-management." (PMID 38628580, 2024). "Furthermore, skipping breakfast can impair insulin function, resulting in higher postprandial plasma glucose levels, which potentially explains why a decreased weekly breakfast frequency is associated with a higher risk of insulin resistance in Korean adults without diabetes or prediabetes." (PMID 39296715, 2024). "The involvement of TRAIL in obesity and diabetes has been reviewed, and while there are many outstanding questions, it is clear that TRAIL plays important roles in adipogenesis, insulin production, and insulin tolerance in mouse models." (PMID 39334884, 2024). "It increases insulin sensitivity; reduces oxidative stress, LDL-c levels, and inflammation; activates the immune system; acts as an anti-atherogenic agent; protects against diabetes; and has neuroprotective effects." (PMID 39273520, 2024). "Moreover, a significant reduction in insulin and C-peptide level; and a significant elevation in FBG and FTA levels was noticed after diabetes induction in GI." (PMID 38461158, 2024). "When we have diabetes, our bodies either do not produce enough insulin or cannot utilize it properly." (PMID 38686006, 2024). "Conversely, type II diabetes mellitus is not insulin-dependent and makes up around 90% of diabetes cases." (PMID 39771551, 2024). "Commonly used anti-diabetic drugs among the diabetes cohort (metformin, sulfonylurea, insulin, and dipeptidyl peptidase-4 inhibitors) were not ranked among the top fifteen important variables." (PMID 39797086, 2024). "In type 2 diabetes mellitus, the body does not secrete/utilize insulin correctly, and a condition of insulin resistance often exists." (PMID 38592298, 2024). "The results showed that GLP could significantly improve the imbalance level of diabetes related indicators in T2DM mice, reduce blood glucose concentration, promote insulin secretion, and improve glucose tolerance." (PMID 39435114, 2024). "On the other hand, the results revealed a lack of knowledge about diabetes pharmacotherapy among the participants, with only 11.1% having some or complete information about their insulin." (PMID 39160425, 2024).